DISC1 (DISC1 scaffold protein)
Diseases named in the same sentence as DISC1 in open-access papers (continued):
Sharing a sentence is not in itself a finding about the gene and the disease.
mental disorder (31 papers, 2011 to 2025). A disease that has its basis in the disruption of mental process. "The decreased levels of DNA methylation in DISC1 have previously been associated with mental disorders." (PMID 41465140, 2025). "Growing biological studies have indicated the relevance of DISC1 in early neurodevelopment and synaptic regulation, suggesting its role in determining multiple endophenotypes underlying major mental disorders." (PMID 36831241, 2023). "Disrupted-In-Schizophrenia 1 (DISC1) is a genetic risk factor implicated in major mental disorders and plays an important role in synaptic and dendritic development in neurons." (PMID 37396784, 2023). "Disrupted-in-schizophrenia 1 (DISC1) is a scaffold protein that has been implicated in multiple mental disorders." (PMID 33542182, 2021). "Pathological DISC1 isoforms disrupt mitochondrial dynamics leading to abnormal neuronal development and DISC1 mutations have been implicated in major mental disorders including MDD and BD." (PMID 30687139, 2018). "Since DISC1 has been identified as a genetic risk for multiple mental disorders, several animal models based on DISC1 have been established using either constitutive neuronal promoters or endogenous DISC1 promoters." (PMID 29156684, 2017). "DISC1 is an especially attractive candidate for such an approach since it is a risk factor for many different mental disorders." (PMID 24027503, 2013). "Multiple iPSC lines have been derived from idiopathic schizophrenia patients and from mental disorder patients with defined genetic lesions, including a 4-bp deletion in the DISC1 locus, a translocation mutation of DISC1, an exonic deletion of Astrotactin-2 and 15q11.2 microdeletions." (PMID 33658519, 2021). "Mutations of DISC1 in the striatum associate with increased METH-induced behavioral sensitization suggesting that DISC1 represents a hub underlying alterations in those DA-dependent molecular mechanisms that modulate reward and sensitization in both drug abuse and mental disorders." (PMID 30061532, 2018). "Disrupted-in-Schizophrenia 1 (DISC1) is a risk gene for a spectrum of major mental disorders." (PMID 25071449, 2014). "Since the discovery of DISC1 as a susceptibility gene for mental disorders, several groups have directed their efforts into creating animal models for these diseases based upon DISC1 modifications per se or in combination with environmental factors such as stress." (PMID 25126062, 2014). "Considering the biological functions of DISC1 protein and the positive results of previous association studies between DISC1 and mental disorders, we hypothesized that DISC1 might be involved in the etiology of autism." (PMID 21569632, 2011). "DISC1 is one of the most promising susceptibility genes for major mental disorders." (PMID 21569632, 2011). "Downstream behavioral consequences in these animals could be of considerable translational interest, as excitatory:inhibitory synapse balance has been proposed as a pathogenic mechanism in major mental disorders, including those associated with disruption of DISC1." (PMID 23826333, 2013). "Though the exact role that DISC1 plays in complex mental disorders is unclear, DISC1 is an important component in the formation of the immune synapse." (PMID 35444632, 2022). "To complement our in vitro patient iPSC model with an in vivo model for behavioral analyses, we generated a humanized mouse model by knocking in the 4-bp deletion in the Disc1 gene at the same position of exon 12 as identified in mental disorder patients." (PMID 33658519, 2021). "Disrupted-in-schizophrenia 1 (DISC1) is one of the best-studied candidate genes for human mental disorders." (PMID 31850339, 2019). "Disrupted-in-schizophrenia-1 (DISC1) is an important genetic factor in serious mental disorders including SZ, BD, and MDD." (PMID 29607311, 2018).
mental disorder (continued). "Our results, by illustrating how missense mutations in DISC1 can lead to specific cellular phenotypes in the hippocampus, support a role for DISC1 variation in brain development, capacity and mental disorder." (PMID 25272038, 2014). "Disrupted-in-Schizophrenia 1 (DISC1) gene is one of the most promising candidate genes for major mental disorders." (PMID 21569632, 2011). "Several other genes that are dysregulated in mental disorders, such as DISC1, phosphodiesterase 4B (PDE4B), and neurexin-1 (NRXN1), could also be impacted by SARS-CoV-2 infection and contribute to neurotropism and inflammation in the CNS." (PMID 35444632, 2022). "We have elucidated the connection between DISC1 and DISC1 pathway proteins such as NRXN1 and PDE4B to viral infection as well as to mental disorders." (PMID 35444632, 2022).
autism (27 papers, 2011 to 2024). Persistent deficits in social interaction and communication and interaction as well as a markedly restricted repertoire of activity and interest as well as repetitive patterns of behavior. "This study found an association between autism and a DISC1 intragenic microsatellite marker and, furthermore, an intragenic three-SNP haplotype and Asperger syndrome." (PMID 23083465, 2012). "To date, several linkage and association studies have confirmed the role of DISC1 in neuropsychiatric disorders, including one study on autism and Asperger syndrome." (PMID 23083465, 2012). "Intriguingly, Disc1 truncation produces callosal abnormalities in mice, and Disc1 single nucleotide polymorphisms are associated with autism, with the strongest association occurring in males." (PMID 21575186, 2011). "Moreover, a DISC1 intragenic microsatellite has been associated with autism, whereas a SNP of DISC1 has been related to Asperger syndrome in Finnish families." (PMID 28331639, 2017). "Interestingly, autism-related mutations in FOXP2 diminished the suppressive effect on DISC1 transcription." (PMID 23083465, 2012). "Most importantly, genetic evidence suggests that DISC1 and TRAX are closely associated with several major mental disorders (such as schizophrenia, autism, and anxiety disorder)." (PMID 30285728, 2018). "Several relevant genetic mouse models of neuropsychiatric disorders emphasize the potential role of reduced neurogenesis on autism-related behaviors, including chromosome 22q11 deletion, mutant Disc1 transgenic mice and Reelin knockout mice." (PMID 21575186, 2011). "Disc1 mutation, carried by BTBR mice, has been related with autism in some cases." (PMID 30150925, 2018). "However, in both the autism model and our DISC1-mutant model, BRN2 levels are decreased, suggesting perhaps additional age-dependent and context-dependent outcomes of disruption of this axis." (PMID 29643329, 2018). "Interestingly, DISC1 is also an ASD candidate gene; variation in DISC1, located at 1q42, was correlated with autism in a Finnish cohort." (PMID 24063311, 2013). "Association studies investigating WNT2, DISC1, MET, DOCK4 or AHI1 also provide evidence that the canonical Wnt pathway might be affected in autism." (PMID 23083465, 2012).
cognitive deficits (25 papers, 2011 to 2025). "DISC1 variants are associated with startle magnitude, P300 deficits, sensory gating deficits, antisaccade deficits, and cognitive deficits." (PMID 28729842, 2017). "Several follow-up studies on multiple mouse models of Disc1 demonstrate that DISC1 perturbation causes significant neurodevelopmental phenotypes, including cognitive defects and psychiatric-like behavioral manifestations." (PMID 27980692, 2016). "In other words, the cognitive deficits are expected to be even more severe when the DISC1 and DAO polymorphisms co-existed in the same cell." (PMID 23555897, 2013). "Various models, including genetic knockout mice and human cell models, have shown that aberrations in DISC1 can result in behavioral changes and cognitive deficits, shedding light on the underlying mechanisms of mental illness and offering potential avenues for therapeutic intervention." (PMID 39194719, 2024). "Third, some genes expressed by progenitors may be dominant; for instance, FVB contain a Disc1 mutation which has been shown to cause cognitive impairment even when heterozygous." (PMID 35906064, 2022). "DISC1’s role as a molecular scaffold suggests that the coordinated expression of DISC1-interactome members is essential for normal brain development and function, and that alteration may result in cognitive deficits and susceptibility to psychiatric illness." (PMID 24940743, 2014). "In line with the observed cognitive impairments, we sought to better understand how DISC1 regulates microglial phagocytic behavior through cytoskeletal remodeling." (PMID 40880479, 2025). "Overexpression of DISC1 at 4‐months of age attenuates accumulation of amyloid plaques, and thus cognitive deficits in these transgenic mice." (PMID 30488644, 2019). "Consistently, DISC1 shows decreased levels in the brains of 8‐month‐old APP/PS1 transgenic mice, which exhibit AD‐like symptoms such as cognitive deficits, accumulation of Aβ, and loss of synapses." (PMID 30488644, 2019). "This is temporally correlated with synaptic deficits of the Disrupted in Schizophrenia-1 (DISC1) protein and the onset of cognitive impairments." (PMID 30352064, 2018). "It is therefore possible that disruptions of DISC1 or HTT resulting in cognitive deficits are the result of alterations in mitochondrial function." (PMID 21298101, 2011). "Furthermore, adolescent stimulation of dopamine neurons also reversed the same cognitive deficits in Disc1+/- mice." (PMID 37830916, 2023). "Multiple mouse models of DISC1 perturbation exhibit cognitive impairments, strengthening the mechanistic link between DISC1 and cognition." (PMID 32029441, 2020). "Altered expression of DISC1 in astrocytes leads to decreased glucose uptake and reduction of lactate production that could be responsible for affective and cognitive disorders consistent with aspects of major mental illnesses." (PMID 29643356, 2018). "Abnormal expression of DISC1 in astrocytes and resulting abnormalities in energy supply may be responsible for aspects of mood and cognitive disorders observed in patients with major psychiatric illnesses." (PMID 29643356, 2018). "Thus, to examine the effects of DISC1‐mediated mitophagy on cognitive deficits, we injected AAV8 encoding DISC1 in the hippocampus of APP/PS1 transgenic mice at 8 months old of age, when these mice already harbored extensive accumulation of amyloid plaques in the brains." (PMID 30488644, 2019). "To evaluate the effects of DISC1‐mediated mitophagy in cognition, we therapeutically express DISC1 in the hippocampus of APP/PS1 transgenic mice at 8 months old of age, when these mice harbor extensive Aβ plaques and loss of synapses, exhibiting cognitive deficits." (PMID 30488644, 2019).
cognitive deficits (continued). "To examine whether overexpression of DISC1 ameliorates cognitive deficits through enhancing mitophagy, we injected bilaterally AAV8 encoding either DISC1, muFSFI, or GFP into the hippocampus of 8‐month‐old APP/PS1 transgenic mice and performed behavioral tests 4 months after injection." (PMID 30488644, 2019). "Because DISC1 is reported to play a critical role in development and migration of hippocampal neurons, cognitive deficits observed in 129 strains may linked to lack of DISC1 protein." (PMID 22238689, 2012).
psychosis (23 papers, 2009 to 2023). "For example, several interesting studies have been conducted using hiPSC-derived forebrain neurons from donors with diagnosis of a familial form of psychosis that carry mutations in the disrupted-in-schizophrenia-1 (DISC1) gene." (PMID 40655966, 2023). "Since then, molecular investigations have highlighted that the liability of the DISC1 gene towards psychosis is mediated by the protein role in processes associated with the pathophysiology of SZ, such as neurodevelopment and neurosignalling." (PMID 35513527, 2022). "We demonstrate that PAK7 is developmentally co-expressed with another known psychosis risk gene (DISC1) suggesting a potential molecular mechanism involving aberrant synapse development and plasticity." (PMID 24474471, 2014). "By conditioning a previous genome-wide association study on DISC1, we have been able to identify eight genes as associating to psychosis proneness." (PMID 22363459, 2012). "Studies of DISC1 and its interactors have established this as one of the most promising pathways underlying psychosis." (PMID 19300510, 2009). "The DISC1 gene is one of the most relevant susceptibility genes for psychosis." (PMID 35513527, 2022). "The in vivo relevance of these effects was confirmed in knock-in mice carrying the human DISC1 mutation, supporting a critical role for cAMP-dependent pathways in DISC1-related psychosis." (PMID 40655966, 2023). "Efforts to characterise such complexity have identified epistatic effects among DISC1 polymorphisms on the susceptibility towards SZ14,22, bipolar disorder, psychosis-related traits, and emotional liability." (PMID 35513527, 2022). "While both humans with psychosis and DISC-1 mice show an enhanced ability to represent the perceptual features of stimuli, they appear unable to use this information to adaptively guide behavior." (PMID 36138518, 2022). "With the discovery of the DISC1 translocation in a large family with high penetrant psychosis in 1990, it was hoped that the genetic architecture of psychosis would quickly emerge." (PMID 27450778, 2016). "We hypothesized that through stratification based on the significant DISC1 variants, we are more likely to identify; due to increased homogeneity in the stratified samples; variants of small effect size that have direct biological relevance to psychosis proneness and potentially interact with DISC1." (PMID 22363459, 2012). "Here, we apply the approach specifically to the DISC1 pathway for additional insight into genetic mediators of psychosis and related biology." (PMID 19300510, 2009). "Although psychosis is a brain disorder, DISC1, NDE1, NDEL1, PDE4B and PDE4D and many other members of the known DISC1 interactome are expressed in lymphoblastoid cell lines." (PMID 19300510, 2009). "DISC1 gene variation may be related to the clinical severity of psychosis at the onset of the disorder." (PMID 36387009, 2022). "Seven psychosis-implicated SNPs across five different genes (proxies of ZNF804A-rs1344706, CACNA1C-rs1006737, BDNF-rs6265, DISC1-rs2793092, DISC1-rs11122319, NRG1-rs6994992 and NRG1-rs35753505 itself) were examined in our independent sample for effects on brain volume." (PMID 36168994, 2022). "Furthermore, given that SZ-like psychosis co-occurs frequently in demyelinating diseases, it is also warranted to investigate the role of DISC1 in pathophysiology of demyelinating diseases such as MS, leukodystrophies and velocardiofacial syndrome." (PMID 24516667, 2014). "After identifying the DISC1 translocation, numerous genetic association studies and meta-analyses have also provided support for the role of Single Nucleotide Polymorphisms (SNPs) and mutations at this gene in the risk for SZ8–11, as well as in other mental disorders and psychosis-related traits." (PMID 35513527, 2022).
psychosis (continued). "Consistently with these suggestions, the disruption of the D2R/DISC1 interaction has been found to reverse hyperactivity and prepulse Inhibition (PPI) aberrations in multiple rodent models of psychosis." (PMID 36979877, 2023).
Anxiety (15 papers, 2013 to 2023). Intense feelings of nervousness, tension, or panic often arise in response to interpersonal stresses. "Together, the results suggest that 1] RIS treatment in WT mice increased anxiety, which was protected by NAP treatment and that 2] the DISC1 genotype showed increased anxiety as compared to WT, which was normalized by NAP treatment but not by RIS treatment." (PMID 26553741, 2015). "This HRM/DISC1 thigmotaxis is a canonical sign of anxiety-like behavior in mice." (PMID 38283751, 2023). "Furthermore, 3] the anxiety state of the mutated DISC1 genotype was not improved by the MIX treatment (i.e. the mix treatment was ineffective)." (PMID 26553741, 2015). "Gomafu can bind to multiple splicing factors and participate in the alternative splicing of DISC1 and ERBB4.Gomafu knockout mice exhibit mild hyperactivity and anxiety-like behavior." (PMID 36226104, 2022).
Alzheimer disease (7 papers, 2016 to 2025). A progressive, neurodegenerative disease characterized by loss of function and death of nerve cells in several areas of the brain leading to loss of cognitive function such as memory and language. "In mouse models of Alzheimer’s disease,rolipram restores dendritic spine density (Smith etal, 2009), while Disc1 mutant mice with impairedDISC1-PDE4B binding show alterations in hippocampal spine density." (PMID 26272049, 2016). "DISC1 also directly affects C-terminal processing of APP and generation of the β-amyloid (Aβ) peptide, a pathological hallmark of Alzheimer’s disease (AD)." (PMID 27370822, 2016). "Second, the role of non-canonical proteins (e.g., transthyretin, DISC1) in proteinjury warrants exploration, particularly in non-Alzheimer’s dementias." (PMID 40463840, 2025).